NDRG1 (N-myc downstream regulated 1)
Diseases named in the same sentence as NDRG1 in open-access papers (continued):
Sharing a sentence is not in itself a finding about the gene and the disease.
cancer (continued). "Even though the exact functions of Ndrg1 protein are still unknown, as another effector in hypoxia-response, it can help cancer cells to survive and grow under unfavourable conditions." (PMID 15341671, 2004). "However, first Ndrg1 expression in normal hypoxic tissue (such as infarct tissues) should be determined to show the cancer specificity of the protein." (PMID 15341671, 2004). "Ndrg1 protein was overexpressed in the majority of cancers studied here." (PMID 15341671, 2004). "However, since the differential expression of Ndrg1 between normal and cancer tissues of lung, brain, and skin was much starker, we propose Ndrg1 be initially tried as a marker for these tissues." (PMID 15341671, 2004). "Therefore, some researchers suggest that NDRG1 may exert pleiotropic effects depending on the cancer type." (PMID 39980566, 2025). "Furthermore, NDRG1 stimulates cell differentiation, growth, stress responses, lipid biosynthesis, and immunity, and inhibits cancer progression, metastasis, and angiogenesis." (PMID 38983911, 2024). "To assess whether NDRG1 is responsible for the anti-cancer effect of the mitochondrially targeted iron chelators and to compare their biological activity, we generated NDRG1 knockout (KO) and overexpressing (OE) clones (CCDS 34945, CCDS59112 and 59,113) in the MCF7 and MDA-MB-231 cells." (PMID 38983911, 2024). "Also, we suggest that once cancer cells have escaped from their primary site and reached distant organs, short exposure to TGFβ1 would be enough to activate NDRG1 and EMT, facilitate colonization, cell proliferation, and chemoresistance by controlling the homeostasis of ALDH1+." (PMID 36594086, 2023). "Additionally, NDRG1 plays pleiotropic roles depending on the type of cancer." (PMID 38235128, 2023). "Herein, we review the potential mechanisms by which NDRG1 might be regulating communication between PaC cancer cells and different components of the TME, providing potential new therapeutic opportunities to re-shape the PaC TME and enhance the efficacy of current treatments." (PMID 37345116, 2023). "Importantly, our results are supported by the hypothesis that NDRG1 has a different interplay with the same molecules in distinct cancers and cell types 8, namely TGFβ1, GSK3β, and NF-κB." (PMID 36594086, 2023). "However, NDRG1 promoting cancer metastasis is consistently found by several investigators." (PMID 35563887, 2022). "The cytoplasmic NDRG1 may exert its effects on cancer stemness and therapeutic resistance." (PMID 35563887, 2022). "In addition to NDRG1 upregulation, iron chelation can inhibit cancer cell stemness." (PMID 36213122, 2022). "On a physiological level, thiosemicarbazones were found to regulate various cancer hallmarks, such as proliferation, epithelial–mesenchymal transition, and migration, many of which are credited to thiosemicarbazones’ ability to induce N-myc downstream regulated gene 1 (NDRG1) expression." (PMID 35008802, 2021). "These latter agents have unique properties allowing the selective targeting and inhibition of cancer cell growth and metastasis through multiple mechanisms, including the depletion of essential metal ions such as iron, which results in the up-regulation of the potent metastasis suppressor, NDRG1." (PMID 34572031, 2021). "Interestingly, Ndrg1 is involved in the regulation of cell proliferation in different cancers." (PMID 33646121, 2021). "Moreover, it is speculated that trypsins cleave NDRG1 in some cancers, abrogating its metastasis suppression capabilities." (PMID 34572031, 2021). "Thus, the potential influence of NDRG1 in cytoskeleton reorganization via regulating actin filament depolymerization might give a better insight into the crucial role that NDRG1 plays in cancer invasiveness." (PMID 33994856, 2021).
cancer (continued). "The molecular mechanism of action of DpT thiosemicarbazones involves the chelation of iron and copper within cancer cells, which is critical for proliferation and the induction of the expression of the potent metastasis suppressor N-myc downstream regulated gene-1 (NDRG1)." (PMID 33334021, 2020). "Our results suggest that the status of GR, Sgk1, and NDRG1 in ESCC patients undergoing NAC was significantly related to the treatment outcomes and that the GR-Sgk1-NDRG1 pathway in carcinoma cells of ESCC might be involved in the clinical effects of chemotherapy in these patients." (PMID 32106831, 2020). "In summary, NDRG1 may be a promising therapeutic target for the treatment of cancer." (PMID 29467385, 2018). "Our data place NDRG1 in the pathway dictating fatty acid utilization by the cell, downstream of both fatty acid synthesis and exogenous uptake, in which NDRG1 negatively regulates fatty acid storage in neutral lipids, and promotes alternative fates in cancer cells." (PMID 29898756, 2018). "Hence, the role of NDRG1 in the formation, development and treatment of cancers may depend on tissue-specific molecular profiles and remains to be clarified." (PMID 28537875, 2017). "The molecular mechanism(s) for NDRG1 on chemosensitivity of cancer cells remains unknown." (PMID 28906492, 2017). "Furthermore, knock-down of NDRG1 expression by siRNA significantly attenuated apoptosis in the cancer cells, implying that NDRG1 may be required for ethyl-3,4-dihydroxybenzoate-induced apoptosis." (PMID 25232961, 2014). "Therefore, proteolytically cleaved NDRG1 protein may be present in only certain types of cancer cells." (PMID 23634903, 2013). "Furthermore, Ndrg1 inhibits cancer cell migration and increases apoptosis in vitro and in vivo." (PMID 22295061, 2012). "The fact that germline mutations of NDRG1 in humans and NDRG1 knockout mouse models do not develop cancers suggests that NDRG1 may not be involved with cancer initiation but at a later event in cancer progression which includes metastasis." (PMID 17786215, 2007). "Therefore, the determination of Ndrg1 protein in tissue samples may provide a more useful tool for cancer diagnosis." (PMID 15341671, 2004). "Therefore, the use of drugs that specifically disrupt the functions of Ndrg1 protein may provide new cancer therapies." (PMID 15341671, 2004). "The determination of Ndrg1 protein levels in cancers may aid the diagnosis of the disease." (PMID 15341671, 2004). "However hypoxia is an equally likely limiting factor in anti-cancer therapy, and Ndrg1 may be simply the signature of the hypoxic state." (PMID 15341671, 2004). "NDRG1, a member of the NDRG family, shows increased expression following treatment with iron chelating agents and in cancer cells." (PMID 40342975, 2025). "The miRNA‐483‐3p target NDRG1 is particularly intriguing as it was identified as a metastasis suppressor in CRC and in several other cancer types." (PMID 36862005, 2023). "More recently, it was discovered that NDRG1 also influences the PaC secretome and subsequent cross-talk with the TME, leading to disrupted cancer-stromal cell communication." (PMID 37345116, 2023). "To confirm the potential effect of this molecule, we transfected the NDRG1-FL plasmid into HNC cells and determined the specific cancer stemness ability presented by spheroid cell formation." (PMID 35563887, 2022). "The expression of SLC6A8 exhibited the strongest positive correlation with that of ADM, GPI, NDRG1, PGK1, and PNCK, and their correlation with SLC6A8 expression in distinct cancer types were illustrated by the heatmap, respectively." (PMID 36061183, 2022).
cancer (continued). "This duplication also recurrently affected known cancer census genes such as CSMD3, COX6C, EXT1, FAM135B, MYC, and NDRG1 in SG1 and SG3 in more than 75% of patients." (PMID 36129940, 2022). "We used pan-cancer RNA-seq data from the UCSC XENA to evaluate the mRNA expression levels of NDRG1 and NDRG2 in diverse human cancers." (PMID 35795037, 2022). "NDRG1 expression is correlated inversely the with survival of GBM patients and is therefore considered a cancer suppressor gene in GBM." (PMID 35448004, 2022). "The pan-cancer analysis results suggest that the eight hub genes (TXNRD1, TUBG1, SF3B4, PPM1G, PIGU, NDRG1, GRPEL2, and EZH2) were differentially expressed in gastrointestinal tumors." (PMID 36686830, 2022). "In sum, these results uncover a mechanism utilized by NDRG1 to regulate CDC42 activity in coordinating cytoskeleton reorganization, which was crucial in cancer invasion." (PMID 33994856, 2021). "NDRG1 is a member of the NDRG family of proteins, and has been extensively shown to have anti-oncogenic and anti-metastatic effects in various cancers, including tumors of the brain, breast, prostate, colon, rectum, esophagus and pancreas." (PMID 34572031, 2021). "Our data suggest that, by stabilizing the complex of RhoGDIα and CDC42, NDRG1 plays a crucial role in keeping CDC42 in the inactive form and thereby prevents filopodia formation and cancer cell invasion." (PMID 33994856, 2021). "Having confirmed the potency of DpC in inducing NDRG1, we tested its effect on EGFR signaling, as was previously reported in carcinoma models." (PMID 35008802, 2021). "To verify if induced hypoxic stress response are common response of cancer cells to chemotherapeutic treatments, we determined the expressions of HIF-1α and NDRG1 after exposure to carboplatin and paclitaxel." (PMID 32550915, 2020). "Among these, the pre-NAC GR status in carcinoma cells was significantly correlated with pStage (P = 0.037), and pre-NAC NDRG1 status was significantly correlated with RECIST grade (P = 0.021) in the patients following NAC." (PMID 32106831, 2020). "To find a possible link between these three cancers subjected to arsenicals exposure, we merged the three networks and identified seven HUB nodes (RXRA, MAP3K7, NR3C1, PABPC1, NDRG1, RELA and CTNNB1) of the linking region between three cancer networks." (PMID 29991691, 2018). "Ingenuity pathway analysis revealed that differentially methylated CpG sites were annotated to genes involved in ‘cell cycling’ (e.g. NDRG1, NEDD1, and MAD1L1), ‘inflammatory diseases’ (e.g. PRTN3), and ‘cancer’ (PCDHA6, MUC4, and ATP2C2)." (PMID 28754985, 2017). "Here we show that NDRG1 is also regulated by the oncogenic MAP kinase-interacting kinase (MNK) pathway, a target for cancer therapy." (PMID 28545025, 2017). "Because focal SCNAs whose sizes were larger than 1 Mbp included an excessive number of genes, we only selected cancer-census genes (MYC and NDRG1) annotated by the COSMIC database from the focal SCNAs (>1 Mbp)." (PMID 28506304, 2017). "Of the differentially expressed proteins, CLU, NDRG1, CD166, S100A11 and Galectin-1 were carcinoma-related proteins affected by rGal3C." (PMID 28701735, 2017). "NDRG1 and NDRG2 have been further shown to be iron chelator responsive genes in a number of cancer cell lines." (PMID 27589737, 2016). "In the NDRG1 module, PSMD2 is overexpressed in many cancer cells, whereas PABPC1, EIF4G1, EIF3H, EIF3E, and EIF3K are RNA translational control members." (PMID 26735889, 2016). "Further, NDRG1 has also been shown to inhibit the TGF-β-induced EMT and to restore membrane β-catenin and E-cadherin levels, which are suppressed by TGF-β in cancer cells." (PMID 26431493, 2015). "Like NDRG1, Nur77 (also called TR3 or NR4A1) is a hypoxia-inducible protein that plays either pro-malignant or anti-malignant roles depending on the cancer cell type and cellular environment." (PMID 26359353, 2015).
cancer (continued). "Thus, genes induced by hypoxia, such as NDRG1, may affect cancer cell survival and metastasis." (PMID 23874544, 2013). "Mechanistically, NDRG1 can interact with Wnt receptor LRP6 and block Wnt/β-catenin signaling in cancer cell lines." (PMID 23741453, 2013). "The present study reviews our current knowledge with regard to the functions of NDRG1 in HCC and other types of human cancer." (PMID 24260043, 2013). "In contrast, in the cancer cell lines displaying high levels of SGK1, we find that NDRG1 phosphorylation is insensitive to Akt inhibitors and knockdown of SGK1 inhibits NDRG1 phosphorylation." (PMID 23581296, 2013). "The first family member, NDRG1, was originally identified as a target repressed by proto-oncogenes MYC and N-MYC and has since been studied under various aliases (e.g., RTP, Rit42, Cap43, PROXY1) in the contexts of cancer, hypoxia, and peripheral neuropathy." (PMID 40462946, 2025). "It is well documented that NDRG1 is phosphorylated at multiple sites by serum- and glucocorticoid-induced kinase 1 (SGK1), which further primes NDRG1 for subsequent phosphorylation by glycogen synthase kinase 3 (GSK3), through which it demonstrates its anti-cancer properties." (PMID 38983911, 2024). "Overall, these results suggest that NDRG1 is mainly involved in the maintenance of TGFβ-induced CSCs, regardless of the origin of cancer cells, and it only has a role in the metastatic ability of cells from metastatic lesions." (PMID 36594086, 2023). "The expression of LPCAT1, NDRG1, G6PD, CYP7A1, SPP1, SFN, and CDCA8 was significantly higher in cancer tissues than in paraneoplastic tissues, whereas the expression of DNASE1L3 was significantly lower in cancer tissues." (PMID 37717019, 2023). "Furthermore, we uncover that TBX2/CoREST targeting of NDRG1 is achieved by recruitment of TBX2 to the NDRG1 promoter by Sp1, the abolishment of which resulted in NDRG1 upregulation and diminished cancer cell proliferation." (PMID 35687133, 2022). "Nevertheless, it has not been established if NDRG1’s expression is inversely related to the survival of cancer cells." (PMID 34142021, 2021). "Finally, NDRG1, also significantly upregulated in ESR1-depleted recurrences and generally expressed in basal cancers, showed differential expression in three distinct LTED cell lines." (PMID 33407744, 2021). "Additional suppressive mechanisms of Dp44mT and DpC on matrix metalloproteases (MMPs) relate to their ability to up-regulate the metastasis suppressors N-myc downstream regulated gene-1 (NDRG1) and NDRG2, which down-regulate MMPs that are crucial for cancer cell invasion." (PMID 32948029, 2020). "It has been described that miRNAs encoded by EBV can downregulate NDRG1, a suppressor of metastasis, to promote EBV-mediated epithelial carcinogenesis, suggesting that NDRG1 plays a negative role in EBV-induced cancer." (PMID 30811506, 2019). "There appears no clear connection in the effect of Ca2+ and HIF-1α on NDRG1 induction in cancer cells." (PMID 28045438, 2017). "As shown, NDRG1 transcript levels were significantly higher in cancer tissues from downstaging patients relative to those from no-downstaging ones." (PMID 28537875, 2017). "Although its biological functions are not entirely clear yet, in one report, Ndrg1 mRNA was reduced in cancer cells compared with normal cells and overexpression of Ndrg1 inhibited cell growth." (PMID 26507712, 2015). "The NDRG1 positive group showed a significant better cancer-free survival rate compared to the NDRG1 negative group (p = 0.000)." (PMID 23874544, 2013). "Intriguingly, Kaplan-Meier analysis showed that CRC patients with NDRG1 negative tumors had significant worse prognosis in both overall survival and cancer-free survival." (PMID 23874544, 2013).
cancer (continued). "Triple-labeled immunofluorescence (BTF3, HINT1 and NDRG1) in tissue array showed a significant (p<0.02) change in co-localization coefficients for BTF3 and NDRG1 co-expression in biochemical relapse vs non-relapse cancer epithelium." (PMID 24386364, 2013). "In brain tissue, Ndrg1 antibody selectively stained cancer cells whereas normal brain remained negative for this staining." (PMID 15341671, 2004). "Thus, Def appears to effectively disrupt processes central to cancer progression, such as metastasis and chemoresistance, potentially through its multifaceted impact on EGFR, ABCB1, and NDRG1 pathways, in support of our initial hypothesis." (PMID 39457585, 2024). "Egr-1 is thought to activate and positively regulate NDRG1 in a variety of cancers; however, in GBM, Egr-1 was not involved in the regulation of NDRG1 expression, indicating that HIF might be the main regulator." (PMID 35448004, 2022). "As suggested for other cancer types, a thiosemicarbazone-mediated decrease in EGFR observed in SH-SY5Y cells in the present study may be attributed to NDRG1 upregulation." (PMID 36160437, 2022). "Consistent with this, anti-cancer iron chelators, Dp44mT and DFO may act via NDRG1-upregulation." (PMID 36357486, 2022). "However, whether NDRG1 may regulate HER2 expression and affect its downstream molecules in HER2-overexpressed cancer cells remains unclear." (PMID 29467385, 2018). "However, the mechanisms by which NDRG1 mediates its effects on cancer cell migration were not fully elucidated and require further investigation." (PMID 25860930, 2015). "HIF-1α was present at higher levels in some cancer cells but not to the extent of Ndrg1." (PMID 15341671, 2004). "This indicates that, at least in these cancer cells, Akt, rather than SGK1, is phosphorylating NDRG1." (PMID 23581296, 2013). "Functional analysis revealed that metixene induced incomplete autophagy through N-Myc downstream regulated 1 (NDRG1) phosphorylation, thereby leading to caspase-mediated apoptosis in both primary and brain-metastatic cells, regardless of cancer subtype or origin." (PMID 37847564, 2023). "The fact that NDRG1 expression was not required for the induction or maintenance of B cell anergy, or other processes of chronic BCR stimulation, enhances the potential for targeting NDRG1 for human anti-cancer treatment." (PMID 36357486, 2022). "NDRG-1 (N-myc downstream-regulated gen-1) controls the negative feedback-loop between the phosphatase and tensin homologue (PTEN) and the phosphoinositide 3-kinase (PI3K) pathway, a balance that usually is lost in cancer and frequently disturbed in PanNET." (PMID 26894863, 2016).